U2 (U2 spliceosomal RNA )
Gene: Small nuclear RNA gene on chromosome 3 (150,241,777 to 150,241,860, forward strand). Ensembl gene ENSG00000278234.
Gene Ontology:
Molecular function: pre-mRNA branch point binding
Biological process: mRNA branch site recognition
Cellular component: U2 snRNP
Homologues: Orthologues: rabbit U2 (77% identical), macaque U2 (65% identical). Paralogues in human: RNU2-2 (76% identical), U2 (76% identical), RNU2-17P (75% identical), RNU2-38P (75% identical), RNU2-3P (75% identical), RNU2-6P (75% identical), RNU2-18P (74% identical), RNU2-4P (74% identical), U2 (74% identical), RNU2-59P (73% identical), RNU2-36P (71% identical), RNU2-52P (71% identical), and 66 more.